MALAT1 (metastasis associated lung adenocarcinoma transcript 1)
Diseases named in the same sentence as MALAT1 in open-access papers (continued):
Sharing a sentence is not in itself a finding about the gene and the disease.
colorectal cancer (continued). "The expression of MALAT1 is upregulated in colorectal cancer (CRC) tissues, and a higher expression level of MALAT1 might serve as a negative prognostic marker in stage II/III CRC patients." (PMID 27782152, 2016).
gastric cancer (160 papers, 2015 to 2025). A primary or metastatic malignant neoplasm involving the stomach. "The results showed that the upregulated MALAT1 expression was associated with accumulation of M2‐polarized macrophages in gastric cancer tissues." (PMID 38639382, 2024). "For this purpose, the effect of the substance on MALAT1 (transcript 1 of metastasis-associated lung adenocarcinoma), whose expression is increased in gastric cancer, was investigated." (PMID 39795061, 2024). "Another lncRNA, metastasis-associated lung adenocarcinoma transcript 1 (MALAT1), has been implicated in gastric cancer metastasis by modulating the expression of genes involved in cell migration and invasion." (PMID 38127056, 2023). "The lncRNA metastasis-associated lung adenocarcinoma transcript 1 (MALAT1) can promote gastric cancer progression via reducing miRNA-124-3p expression and subsequent induction of EZH2 signaling." (PMID 35236381, 2022). "It has been reported that exposing gastric cancer cells to hydrogen is associated with down-regulation of MALAT1, and subsequent upregulation of miRNA-124-3p as a tumor-suppressor, resulting in EZH2 inhibition and suppression of proliferation and invasion." (PMID 35236381, 2022). "LncRNA metastasis-associated lung adenocarcinoma transcript 1 (MALAT1), located at chromosome 11q13, has been reported to be a key participant in the Propofol-mediated mechanism in gastric cancer." (PMID 34266379, 2021). "In another report, gastric cancer was detected via the overexpression of the lncRNA metastasis-associated lung adenocarcinoma transcript 1 (MALAT-1)." (PMID 31993365, 2019). "In gastric cancer GLI2 is upregulated due to the upregulation of lncRNA metastasis associated lung adenocarcinoma transcript 1 (MALAT1)." (PMID 30158435, 2018). "Metastasis-associated lung adenocarcinoma transcript 1 (MALAT1) increases the tumorigenesis and metastasis of gastric cancer via facilitating vasculogenic mimicry and angiogenesis." (PMID 29773901, 2018). "In particular, the metastasis-associated target gene, RASSF6, a member of the RAS-association domain family, is downregulated in gastric cancer, and its expression was upregulated by MALAT1 silencing, as revealed by genome-wide gene expression analysis." (PMID 28077118, 2017). "Univariate and multivariate analysis of plasma MALAT1 and clinicopathologic factors associated with survival in gastric cancer." (PMID 27486823, 2016). "Moreover, in gastric cancer, the upregulation of MALAT1 has been associated with the inhibition of miR‐370‐3p expression, thereby facilitating tumour cell proliferation and invasion." (PMID 39347925, 2024). "In addition, it was found that lncRNA MALAT1 expression was associated with the presence of vasculogenic mimicry and endothelial vessels in gastric cancer tissues." (PMID 32466537, 2020). "In gastric cancer cells, propofol facilitated apoptosis and reduced autophagy‐related chemoresistance to cisplatin via inhibition of lncRNA metastasis‐associated lung adenocarcinoma transcript 1 (MALAT1)." (PMID 32596964, 2020). "Besides, lncRNA metastasis-associated lung adenocarcinoma transcript 1 (MALAT1) was overexpressed in gastric cancer cells and promote cell proliferation in gastric cancer by recruiting SF2/ASF." (PMID 32509569, 2020). "In gastric cancer, the expression of MALAT1 was associated with VM density and endothelial vessels." (PMID 32169087, 2020). "The mechanisms underlying the aberrant expression of MALAT1 in gastric cancer remain elusive." (PMID 27486823, 2016). "Metastasis-Associated Lung Adenocarcinoma Transcript 1 (MALAT1) represents a lncRNA that exhibits notable overexpression across many cancer forms, such as gastric cancer (GC), esophageal cancer (EC), and non-small cell lung cancer (NSCLC)." (PMID 39323624, 2024).
gastric cancer (continued). "Among these, metastasis-associated lung adenocarcinoma transcript 1 (MALAT1), also known as nuclear-enriched abundant transcript 2, promotes angiogenesis and VM formation in patients with gastric cancer." (PMID 40277941, 2025). "MALAT1 in gastric cancer also inhibits autophagy flux and stimulates IL-6 by regulating the PTEN/AKT/mTOR pathway, thereby transforming fibroblasts into myofibroblasts." (PMID 40297152, 2025). "MALAT1’s elevated expression strongly correlates with poor prognosis in gastric cancer, highlighting its potential as a therapeutic target, particularly for RNA interference-based treatments." (PMID 41220952, 2025). "demonstrate that MALAT1 mediates glycolytic regulation to promote the progression of gastric cancer." (PMID 40728857, 2025). "To uncover the mechanism for the roles of M2‐EX‐derived MALAT1 in gastric cancer progression, we predicted the potential interacting proteins of MALAT1 by using catRAPID software." (PMID 38639382, 2024). "We also validated that MALAT1 was enriched in exosomes from human peripheral blood monocyte‐derived M2‐polarized macrophages, and aerobic glycolysis was induced to promote gastric cancer cell proliferation, migration, invasion, and chemoresistance." (PMID 38639382, 2024). "The promotion of gastric cancer cell proliferation, migration, and invasion by M2‐EX was also attenuated by MALAT1 knockdown." (PMID 38639382, 2024). "To confirm this, we performed a cycloheximide (CHX) assay to evaluate the half‐life of δ‐catenin protein in gastric cancer cells treated with si‐NC and si‐MALAT1 M2‐EX at different times." (PMID 38639382, 2024). "More importantly, we found that the protection against both oxaliplatin‐ and cisplatin‐induced cell apoptosis and the increases in IC50 of gastric cancer cells to oxaliplatin and cisplatin by M2‐EX were reduced by MALAT1 knockdown." (PMID 38639382, 2024). "In summary, these data suggest that M2‐EX‐derived MALAT1 upregulates HIF‐1α by sponging miR‐217‐5p in gastric cancer cells." (PMID 38639382, 2024). "An experiment on the BGC823 cell line confirmed that Res inhibited the migration and invasion of human gastric cancer cells by inhibiting MALAT1-mediated epithelial-to-mesenchymal transition." (PMID 39795061, 2024). "Many oncogenic lncRNAs, including nuclear paraspeckle assembly transcript 1 (NEAT1), MALAT1, UCA1, and prostate cancer-associated transcript 1 (PCAT-1), as well as some tumor suppressor lncRNAs, have been shown to play a role in gastric cancer chemoresistance." (PMID 38294554, 2024). "LncRNA MALAT1 is one example in which silencing MALAT1 in gastric cancer cells triggered autophagy via mTOR inhibition, thereby suppressing cell proliferation." (PMID 39392103, 2024). "RT‐PCR and western blot results showed that, compared to the SI‐NC group, the upregulation of glycolysis‐related genes PKM2, GLUTA, HK2, and LDHA in gastric cancer cells was reversed in the si‐MALAT1 groups." (PMID 38639382, 2024). "We further detected the correlation between MALAT1 and M2‐polarized macrophages in gastric cancer tissues." (PMID 38639382, 2024). "Compared to the unmodified exosomes, RGD; M2pep‐293T‐EX were more efficiently uptaken by gastric cancer cells and M2 TAMs and remarkably led to the inhibition of MALAT1 expression in both cells." (PMID 38639382, 2024). "The CM from gastric cancer tissues derived M2 TAMs also enhanced glycolysis in gastric cancer cells but this effect was abolished by MALAT1 knockdown." (PMID 38639382, 2024). "We also found that M2‐EX‐derived MALAT1, when internalized by gastric cancer cells, co‐localized with δ‐catenin in the cytosol." (PMID 38639382, 2024). "The widely recognized mechanism of these effects was that MALAT1 can act as a ceRNA for miRNA like miR-23b-3p to attenuate the inhibitory effect of miRNA, leading to chemo-induced autophagy and chemoresistance in gastric cancer cells." (PMID 38561330, 2024).
gastric cancer (continued). "They further constructed an exosome‐mediated delivery of siRNA system for dual‐targeted inhibition of MALAT1 in both gastric cancer cells and macrophages, which remarkably suppressed gastric cancer growth and improved chemosensitivity in mouse tumor models." (PMID 38639382, 2024). "We observed that M2‐EX treatment upregulated δ‐catenin protein expression in gastric cancer cells, while this phenomenon was weakened by MALAT1 knockdown in M2‐polarized macrophages." (PMID 38639382, 2024). "Taken together, these results indicate that RGD; M2pep‐293T‐EX‐SI‐1 efficiently suppresses MALAT1 expression and suppresses gastric cancer progression." (PMID 38639382, 2024). "Taken together, these results suggest that M2 TAMs‐derived exosomes promote gastric cancer progression via MALAT1‐mediated regulation of glycolysis." (PMID 38639382, 2024). "Previous research has also demonstrated that EBV infection can modulate the expression of various lncRNAs, such as SNHG8 in gastric cancer and MALAT1, AFAP1-AS1, and AL359062 in nasopharyngeal carcinoma." (PMID 39684278, 2024). "We further transfected M2‐polarized macrophages with Cy3‐labeled MALAT1 and collected their derived exosomes to incubate with gastric cancer cells." (PMID 38639382, 2024). "The regulatory role of MALAT1 in oxaliplatin (OXA) resistance in gastric cancer cells is mediated by its interaction with ZFP91 through miR-22-3p sponging." (PMID 38370477, 2024). "It is identified that MALAT1 (metastasis‐associated lung adenocarcinoma transcript 1) is enriched in M2 TAM exosomes and confirmed that MALAT1 transfer from M2 TAMs to gastric cancer cells via exosomes mediates this effect." (PMID 38639382, 2024). "In summary, these results indicate that exosomes from M2‐polarized macrophages induce aerobic glycolysis and promote gastric cancer cell proliferation, migration, and invasion through the transfer of MALAT1." (PMID 38639382, 2024). "We observed that M2‐EX treatment decreased miR‐217‐5p expression in gastric cancer cells while MALAT1‐depleted M2‐EX had a minimal effect." (PMID 38639382, 2024). "For instance, MALAT1 was increased in gastric cancer and acts as an oncogene to enhance the resistance to oxaliplatin." (PMID 36793374, 2023). "Patent applications were filed by some researchers for the use of HOTAIR and MALAT1 (CN105586399A) as adjunctive biomarkers in gastric cancer." (PMID 38813489, 2023). "The UPF1 inhibition of gastric cancer progression was reduced by high levels of MALAT1, demonstrating a promising target for gastric cancer treatment." (PMID 36766761, 2023). "In a study of gastric cancer, it was found that high expression of MALAT1 resulted in lower survival rates compared to the normal group." (PMID 38813489, 2023). "MALAT1 regulates chemotherapy resistance related to autophagy in gastric cancer by targeting miR-23b-3p." (PMID 36793374, 2023). "Although microRNA analysis showed the potential role of MALAT1 in gastric cancer pathogenesis, there are presently few studies available on this subject." (PMID 35650297, 2022). "In contrast, UPF1 inhibited the expression of MALAT1 in gastric cancer by accelerating its degradation." (PMID 35318304, 2022). "Overexpression of MALAT1 accelerates the growth of gastric cancer cells and enhances the ability of tumor cells to invade and metastasize." (PMID 36246567, 2022). "In contrast, MALAT1 rs3200401 has been found to be correlated with histological type of gastric cancer." (PMID 35517413, 2022). "Some identified oncogenic lncRNAs overexpressed in gastric cancerous tissue, such as H19, HOTAIR, and MALAT1, whereas others are expressed in the tissue from gastric carcinoma at a low level, such as LincRNA-p21, LINC00261, CTLSP4 and SPRY4-IT1." (PMID 36310592, 2022). "LncRNA MALAT1 also alleviated H2 caused inhibition of the proliferation and migration of MGC-803 and BGC-823 gastric cancer cells." (PMID 33482814, 2021).
gastric cancer (continued). "These suggested that MALAT1 expression has the potential to impact gastric cancer patient prognosis in early stage." (PMID 34308750, 2021). "Because of the MALAT1 high expression in gastric cancer patients, we next explored the relationship between MALAT1 RNA level and clinicopathological features using KM plotter databases to understand the underlying mechanisms." (PMID 34308750, 2021). "UPF1 binds to MALAT1 and promotes its degradation, thereby inhibiting the expression of MALAT1 in gastric cancer." (PMID 33732285, 2021). "LncRNA MALAT1 was overexpressed in gastric cancers compared to adjacent normal tissue and promoted gastric cancer cells proliferation, migration, and resistance to cisplatin through activating PI3K/AKT pathway." (PMID 33482814, 2021). "Especially, MALAT1 high RNA level was related to the early stage in lung and gastric cancer patients." (PMID 34308750, 2021). "This study demonstrated that H2 gas curbed gastric cancer growth in vivo and gastric cancer cell proliferation and migration in vitro by reducing lncRNA MALAT1 level, which in turn upregulated miR-124-3p and downregulated EZH2 expression." (PMID 33482814, 2021). "Especially, we also found that upregulation of MALAT1 RNA level was related to early stage in lung and gastric cancer patients." (PMID 34308750, 2021). "Reportedly, MALAT1 expression is significantly upregulated in lung cancer, glioblastoma, gastric cancer, as well as other tumors." (PMID 34660566, 2021). "MALAT1 was shown to directly bind to and stabilize Sox2 mRNA, which led to the increase of stemness and chemo-and radioresistance of gastric cancer cells." (PMID 33482814, 2021). "Propofol reducing the expression of MALAT1 has also been demonstrated in gastric cancer, in which Propofol decreased the expression of MALAT1 to promote the sensitivity of gastric cancer cells to cisplatin." (PMID 34266379, 2021). "lncRNA MALAT1 activates autophagy and promotes the cell proliferation by downregulating the miRNA-204 expression in gastric cancer." (PMID 33869042, 2021). "For instance, MALAT1 facilitates the development of gastric cancer through activation of the phosphoinositide 3-kinase (PI3K)/AKT pathway." (PMID 34660566, 2021). "The current study demonstrated that lncRNA MALAT1 promoted gastric cancer proliferation and migration through modulating miR-124-3p/EZH2 axis." (PMID 33482814, 2021). "Silencing MALAT1 can inhibit chemically induced autophagy, while overexpression of MALAT1 can promote autophagy in gastric cancer." (PMID 34821640, 2021). "Researchers have demonstrated that UPF1 inhibits the expression of MALAT1 in gastric cancer and inhibits tumor development by targeting MALAT1." (PMID 34520393, 2021). "LncRNA MALAT1 enhanced the stemness, proliferation, migration, invasion, and drug resistance of gastric cancer cells." (PMID 33482814, 2021). "Among them, MALAT1 was shown to regulate chemoresistance via miRNA-23b-3p sequestration in gastric cancer." (PMID 32993558, 2020). "This study aimed to assess the associations of lncRNA ANRIL, H19, MALAT1, MEG3, HOTAIR single-nucleotide polymorphisms (SNPs) with gastric cancer and atrophic gastritis." (PMID 33333725, 2020). "The lncRNA MALAT1 served as a competitive endogenous RNA, sponging miRNAs, including miR-202 (in gastric cancer) and miR-200c (in endometrioid endometrial carcinoma)." (PMID 32393270, 2020). "This study aimed to examine associations of lncRNA ANRIL (rs17694493, rs1333045, rs1011970), H19 (rs217727), MALAT1 (rs3200401), MEG3 (rs1054000), and HOTAIR (rs17840857) polymorphisms with gastric cancer and atrophic gastritis in European population." (PMID 33333725, 2020). "Silencing of MALAT1 suppresses chemotherapy-induced autophagy and sensitizes gastric cancer cells to chemotherapeutics." (PMID 32174966, 2020). "Compared with parental counterparts, chemotherapy-resistant gastric cancer cells show higher levels of MALAT1 and autophagy." (PMID 32174966, 2020).
gastric cancer (continued). "Earlier investigations concluded that MALAT1 expression is upregulated in many tumors, including those of bladder cancer, ovarian cancer, gastric cancer, osteosarcoma, and pancreatic cancer." (PMID 31101802, 2019). "Among them is the metastasis-associated lung adenocarcinoma transcript 1 (MALAT1), which is downregulated in gastric cancer upon UPF1 overexpression." (PMID 30916337, 2019). "This dysregulation of lncRNA MALAT1 has also been identified in other human diseases, such as gastric cancer and pulmonary arterial hypertension." (PMID 31343412, 2019). "GAS5 and MALAT1 modulate chemo resistance in gastric cancers and glioblastoma multiforma cells, respectively." (PMID 31141943, 2019). "Expression levels of MALAT1 in six common solid malignant cell lines (stomach carcinoma: SGC‐7901 and NCL‐N87; hepatocarcinoma: HepG2 and Huh‐7; prostate cancer: DU145 and LNCaP) were detected." (PMID 31466138, 2019). "Another study has found that lncRNA MALAT1 promotes the invasion of gastric cancer cells via binding to the core protein complex PRC2 and inhibiting PCDH10." (PMID 29599647, 2018). "We also performed Spearman correlation test between lncRNAs and mRNAs and observed that BC032469, MALAT1, PTENP1-AS, and PANDA had a significant correlation with gastric cancer-associated genes." (PMID 29719612, 2018). "These suggested that miR-139 was not likely to have canonical miRNA repression on gomafu, which were similar with the mode of miR-23b-3p and MALAT1 in gastric cancer cells." (PMID 29459686, 2018). "LncRNA MALAT-1 is highly expressed in gastric cancer cells resistant to 5-fluoruracil and cis-platin, respectively, compared to parental gastric cancer cells." (PMID 29967761, 2018). "Silencing of MALAT1 inhibited chemo-induced autophagy, whereas MALAT1 promoted autophagy in gastric cancer cells." (PMID 29162158, 2017). "In conclusion, we demonstrated that MALAT1 was significantly overexpressed in gastric cancer tissues and cell lines and revealed a MALAT1/miR-1297/HMGB2 regulator pathway in GC." (PMID 28396617, 2017). "(c) ChIP assays detected the H3K27Ac acetylation at promoter of MALAT1 in gastric cancer cells.*, p < 0.05, **, p< 0.01." (PMID 29162158, 2017). "To determine the relationship between advanced stage and MALAT1, we explored the invasion and migration of gastric cancer cells using siRNA for MALAT1." (PMID 28077118, 2017). "The expression of MALAT1 was significantly higher in gastric cancer tissues than in adjacent normal tissues." (PMID 28077118, 2017). "The level of MALAT1 was measured in 19 gastric cancer cell lines and compared to normal epithelial gastric GES-1, 5 normal gastric tissues adjacent to cancer and rat normal gastric surface mucous cell (RGM-1)." (PMID 28077118, 2017). "Based on the microarray analysis, we evaluated the impact of MALAT1 on apoptosis and cell proliferation as indicators of carcinogenesis in gastric cancer." (PMID 28077118, 2017). "High expression of MALAT1 in gastric cancer correlated with advanced T stage, which was supported by the finding that Inhibition of MALAT1 decreased cell invasiveness and migration." (PMID 28077118, 2017). "The main objective of this study was to investigate the expression level and biological function of MALAT1 in gastric cancer (GC)." (PMID 28396617, 2017). "In the study, we found the expression level of MALAT1 was significantly higher in gastric cancer tissues compared with adjacent normal tissues." (PMID 28396617, 2017). "Three different siRNAs were tested to knock down MALAT-1 in three different gastric cancer cell lines." (PMID 28077118, 2017). "The expression of MALAT1 was upregulated in gastric cancer cell lines relative to levels in GES-1, 5 normal gastric tissues and RGM." (PMID 28077118, 2017). "MALAT1 was aberrantly highly expressed in GC cell lines and promoted cell proliferation in gastric cancer by recruiting SF2/ASF." (PMID 28396617, 2017).